FGFR1 (fibroblast growth factor receptor 1)
Diseases named in the same sentence as FGFR1 in open-access papers (continued):
Sharing a sentence is not in itself a finding about the gene and the disease.
tumor (continued). "In the FGFR1-amplified cell line MDA-MB-134, treatment with an anti-FGFR1 antibody reduced the phosphorylation of FRS2 and ERK1/2 downstream of the receptor, which resulted in the reduction of tumour growth in pre-clinical models." (PMID 35193394, 2022). "This revealed that GPx2 KD further enriched cluster 5 in basal/mesenchymal-like genes (KRT14, ITGA6, FGFR1, COLA9A3, S100s) relative to cluster 5 in control tumor." (PMID 35193955, 2022). "Wnt1/FGFR1 mice showed significantly enhanced myeloid-derived tumor suppressor cells (MDSC) infiltration and tumor angiogenesis compared to single Wnt1 transgenic mice." (PMID 36147913, 2022). "At the same time, FGFR1 and TLR4 regulate tumor cell hyperplasia and migration and promote proinflammatory response production via the PI3K/Akt signaling pathway." (PMID 35342418, 2022). "Nevertheless, FGFR1 and FGFR4 expression levels were increased and approximated to expression in tumor-adjacent normal tissue (fold-change, ~1) in individual tumor samples: 3 (15%) and 1 (5%), respectively." (PMID 36142417, 2022). "In PDAC cells, combined PARP and Fibroblast Growth Factor Receptor 1 (FGFR1) inhibition via PD173074 is synthetic lethal in vitro, showing improved efficacy in tumor xenografts compared to either approach in monotherapy." (PMID 35205643, 2022). "From the tested drugs reported thus far, DNA-interfering trabectedin and the multi-tyrosine kinase inhibitors (TKIs) ponatinib, dasatinib, and nintedanib, as well as the more FGFR1-specific PD173074, showed pronounced activity against SFT tumor growth." (PMID 36428694, 2022). "On the other hand, fibroblast growth factor receptor 1 (FGFR1) is commonly expressed in all types of cancer and is involved in tumor progression and epithelial-to-mesenchymal transition-related drug resistance to EGFR-TKIs." (PMID 36015232, 2022). "Accordingly, these tumors show increased sensitivity to FGFR1 and PI3K inhibition, and this is a therapeutic vulnerability through restoring the tumor-suppressive function of 4EBP1." (PMID 35626002, 2022). "The crosstalk between FGFR1 and other signalling pathways in responding to changes of the environment is also exemplified by data showing that the inhibition of both FGFR1 and VEGFR is more efficient in reducing tumour angiogenesis than either treatment alone." (PMID 35193394, 2022). "Our findings revealed significantly decreased FGFR1 and FGFR4 mRNA expression in tumor tissue compared with tumor-adjacent normal tissue." (PMID 36142417, 2022). "Amplifications of FGFR1, FGF9, or FRS2 were discovered in 3 out 28 (10.7%) tumors of patients with ENSAT tumor stage III–IV by comparative genomic hybridization." (PMID 35583844, 2022). "The stromal-rich tumor subgroup had low pCR (1/9; 12.5%), with the only exception in the stromal cluster having again high KRT20 and low FGFR1 expression, indicating the limitation of the cluster method." (PMID 35887247, 2022). "Moreover, the FGFR1 signalling pathway may be crucial in tumour cell invasion." (PMID 36497187, 2022). "FGF/FGFR1 signaling induces glycolysis and FGFR1 phosphorylates LDHA, where FGFR1 expression induces p-LDHA level and activates LDHA activity in tumor cells." (PMID 36077431, 2022). "In both studies, ~ 11% of patients with FGFR1-amplified Sq-NSCLC achieved PR (4/36 and 3/26, respectively) with a decrease in tumor size of ~ 30–40%, and ~ 40% of patients had SD." (PMID 35402233, 2022). "FGFR1 and FGFR4 gene expression levels were significantly decreased in tumor samples (n = 20) compared with tumor-adjacent normal tissue (n = 20): FGFR1 (p = 0.0002) and FGFR4 (p = 0.000001)." (PMID 36142417, 2022).
tumor (continued). "FGFR1 and FGFR4 mRNA levels are significantly decreased in Sq-NSCLC tissue compared with tumor-adjacent normal tissue." (PMID 36142417, 2022). "It first released CQ to reduce the autophagy of tumor cells, and then released PD173074 to inhibit FGFR1 activity." (PMID 33511016, 2021). "Unlike the parent molecule, however, p700 exhibits a broader binding specificity for other growth factor receptors such as VEGFR1, VEGFR3, PDGFRα, FGFR1, FDFR2α, FDFR3 and FDFR4, all of which are highly expressed in tumours or tumour vasculature." (PMID 33504102, 2021). "In a recent study, anlotinib mainly inhibited angiogenesis and tissue tumour cell migration by inhibiting c-Kit, VEGFR2, VEGFR3, FGFR1-4, PDGFR α and β, and other targets, thus inhibiting tumour." (PMID 34926131, 2021). "When FGFR1 binds to different FGF ligands, FGFR1 can activate PKC, MAPK and PI3K/Akt pathways and participate in tumour development." (PMID 34350720, 2021). "Levatinib is a MKI targeting VEGFR 1–3, fibroblast growth factor receptor 1–4, platelet derived growth factor receptor, RET and KIT with similar anti-tumor activity to sorafenib." (PMID 33923463, 2021). "Whole genome microarray analysis revealed the upregulation of angiogenesis-related genes including bFGF, FGFR1-3, PLCg2, FZD4, CX3CL1 and CCL5 in the bevacizumab-resistant tumor cells." (PMID 33804681, 2021). "We demonstrate a requirement for the scaffold protein FRS2 downstream from both Met and FGFR1 and find that dual inhibition of MET and FGFR1 signalling results in TIC depletion, hindering tumour progression." (PMID 33772015, 2021). "Here, we show that combined treatment with fibroblast growth factor receptor 1 (FGFR1) and polo‐like kinase 1 (PLK1) inhibitors evoke synergistic cytotoxicity in KRAS‐mutant tumor models in vitro and in vivo." (PMID 34369083, 2021). "Tumor cells expressed relatively high levels of EGFR, FGFR1, and FGFR2, while their corresponding ligands, such as COPA, GRN, HBEGF, FGF2, FGF7, and FGF18, were widely expressed in fibroblast cells." (PMID 34459128, 2021). "The use of anti-FGFR1 antibody reduces AKT phosphorylation, inhibits tumor growth and restores drug sensitivity both in vitro and in vivo." (PMID 34830951, 2021). "Taken together, these data strongly suggest that enhanced expression of FGFR1 inhibits T-DM1 binding, facilitating therapeutic persistence of HER2+ cells and post-treatment tumor recurrence." (PMID 33479246, 2021). "Most of these tumor-related alterations belong to the kinases from the closest animal counterpart RTKs, such as RON, FGFR1-4, IGF-1R, ALK, c-Ret, c-Met, and HER-2." (PMID 35095975, 2021). "A possible reason is the wide range of tumor cell targets affected (VEGF, VEGFR1–3, FGFR1–4, PDGFRα, KIT, and RET)." (PMID 34630336, 2021). "This was supported by the frequent (~30%) co-amplification of FGFR1 and cyclin D1/CCND1, as well as a cyclin D1 upregulation in the tumor tissues, that was examined." (PMID 34831231, 2021). "Here we show that zotatifin downregulates protein expression of FGFR1/2 and HER2 oncogenes, across a range of solid tumor models, resulting in potent anti-tumor activity and in vivo tumor growth inhibition and regression." (PMID 34900714, 2021). "PTBP1 was originally identified as an SF and a promoter in multiple cancers by regulating oncogenes or tumor suppressors, including PKM2, MRP1, and FGFR1." (PMID 34290732, 2021). "The finding that FGFR1 is hardly expressed and NTRK1 mRNA expression is high provides clear evidence for the anti-tumor effect of AZD4547 in KM12(Luc) (TPM3-NTRK1)." (PMID 34790577, 2021). "We then established H358 cells overexpressing FGFR1 (H358-FGFR1OE), and, as expected, forced expression of FGFR1 diminished the cytotoxicity of ARS-1620, whereas combined treatment with ARS-1620 and AZD4547 enhanced the tumor cell-killing effect." (PMID 34858498, 2021).
tumor (continued). "Our data and existing literature together suggest a regulatory axis involving FGFR1, WNT/ β-catenin signaling, and tumor immune microenvironment in regulation of NB cell lines." (PMID 35068946, 2021). "Sorafenib is a multikinase inhibitor that targets the Raf/MAPK/ERK signaling pathway, interfering with the tyrosine kinases VEGFR-2/3, PDGFR-β, B-Raf, c-Raf, FGFR1, Flt3, c-KIT, RET, and p38 α, and induces tumor cell apoptosis in HCC." (PMID 33808407, 2021). "In 2019 a metastatic sample from the liver was sent for GEM ExTra® testing which identified ATM (Y370fs), FGFR1 amplification, and an FGFR1/G3BP2 fusion in the metastatic tumor sample." (PMID 34504655, 2021). "While fibroblast cells, like tumor cells, expressed EGFR and FGFR1, they also exclusively expressed higher levels of the receptors LRP1, PDGFRs, and PLXND1 in both patients." (PMID 34459128, 2021). "According to Wilcoxon test, both FGFR1 (p = 0.0001) and GLI1 (p = 0.0001) were significantly overexpressed in tumor samples compared to their respective controls." (PMID 34722544, 2021). "Lenvatinib, a kinase inhibitor, exerts its antitumor effects by inhibiting angiogenesis, which is important for tumor growth and metastasis, mainly by inhibiting VEGFR1–3 and FGFR1–4." (PMID 34176067, 2021). "These trials included multiple tumor types and suggested that FGFR overexpressing cancers through FGFR mRNA levels tended to benefit from small molecule inhibitors of FGFR1-4 such as rogaratinib." (PMID 33626078, 2021). "The bi-directional cross-talk between CAF and tumor cells involves putative secretory signaling proteins such as TGF-beta 2, FGF2 (from CAF), and FGFR1 (from tumor cells)." (PMID 34502029, 2021). "Importantly, given the association between enhanced stemness and FGFR1-induced palbociclib resistance, our results also suggest that assessment of various strategies targeting FGFR deregulation-associated CDKi resistance should include biomarkers that can evaluate CSC stemness in tumor treatment." (PMID 34831231, 2021). "Therefore, while the identification of an FGFR1 alteration in a CNS tumor of uncertain subtype may help to narrow the differential diagnosis and exclude certain tumor entities, this single genetic finding in and of itself does not enable precise classification." (PMID 32859279, 2020). "Genomic heterogeneity of copy number alteration in tumour #1 and tumour #2 was observed in 7 (33%) of 21 patients including ERBB2 in two patients (patients 9 and 19), FGFR1 in two patients (patients 3 and 13), and FGFR2 in one patient (patient 4)." (PMID 31929516, 2020). "We performed ISH to confirm the results of ERBB2, FGFR1, and FGFR2 status in the two lesions, and we confirmed amplification in either tumour #1 or tumour #2." (PMID 31929516, 2020). "We identified six survival-related genes, EMP1, TPM1, NRP2, FGFR1, CAVIN1, and LATS2, found in the DEG analyses of both, tumor-paracancerous and paracancerous-normal differentially expressed data sets." (PMID 32695477, 2020). "For 23 cases, the same level of FGFR1 and/or FGFR4 expression was detected between the primitive tumor and the recurrences." (PMID 33092134, 2020). "For example, over 30% patients had positive FGFR1 expression in UCEC, OV, KICH, and ACC, whereas the positive ratios of FGFR3 were very low in these tumor types." (PMID 32596330, 2020). "Given that all quadruple WT GISTs expressed both FGFR1 and FGFR2, and showed phosphorylated-AKT, the existence of an oncogenic autocrine loop supporting tumor growth is conceivable." (PMID 32392832, 2020).
tumor (continued). "In each case, 2 patients (4.8%) harbored CNV in all 3 exons of EGFR and FGFR1, and only one patient (2.4%) had CNV in both exons of TOP2A, suggesting that the whole genes were possibly amplified in the primary tumor." (PMID 33298978, 2020). "Conversely, regorafenib, a novel oral MKI, blocks several protein kinases involved in the tumor angiogenesis (VEGFR-1, -2, and -3), tumor growth (KIT, RET, RAF-1, and BRAF), and metastasis (PDGFR-β, FGFR1) of cancer cells." (PMID 32466169, 2020). "Co-culture of BMDM with MC38 or KPC tumour cells led to increased expression of FGFR1 and 2 on BMDM and this increase was greater if the tumour cells had been irradiated." (PMID 32792542, 2020). "Compared with FGFR1 and 3, positive ratios of FGFR2 or 4 were generally lower in most of the tumor types, except in CHOL and LIHC." (PMID 32596330, 2020). "The in vivo anti-tumour activity of volasertib was assessed in comparison with the CDK4/6 inhibitor palbociclib and the FGFR1/2/3 inhibitor AZD45479, as monotherapies or in combination with fulvestrant." (PMID 32792481, 2020). "The FGFR1/CEN8 ratio ranged from 1.1–8.4, with an average number of FGFR1 gene signals per tumor cell of 4.3 ranging from 4.8–25.1." (PMID 32517171, 2020). "Interestingly, the tumor was shown to overexpress FGFR1 and FGFR4 supporting our hypothesis." (PMID 33092134, 2020). "Next, the potent dual inhibitor—namely, 3D185, which targets FGFR1-3 and colony stimulating factor 1 receptor (CSF1R)—showed promising anti-tumor effects in FGFR-dependent and macrophage-dominant cancer models." (PMID 33081025, 2020). "In particular, FGFR1 amplification was determined as an independent factor for disease progression and thus, may be involved in the invasion, metastasis, and drug resistance of tumor cells during the development of treatment-resistant, aggressive, advanced hypopharyngeal and laryngeal SCCs." (PMID 32326908, 2020). "The results indicated that FGFR1, MYPT1, and LDHB are relevant to disease progression, i.e., FGFR1 is negatively correlated with tumor progression whereas MYPT1 and LDHB are positively correlated with tumor progression in tumor-adjacent stroma." (PMID 31316912, 2019). "We investigated the profiles for six protein markers, FGFR1, FRS2, S6K1, LDHB, MYPT1, and P-LDHA, in tumor-adjacent stroma." (PMID 31316912, 2019). "It should be noted that copy gains of EGFR, FGFR1, MET, and ERBB2 have already been reported to be predictive markers for certain tumor types." (PMID 31480645, 2019). "Therefore, we speculate that FGFR1-derived circRNAs may act as tumor promotors in NSCLC." (PMID 31815619, 2019). "In contrast, the upregulated DEGs included both caner-drivers/oncogenes, e.g. FGFR1 and MAP3K8, and tumor suppressors, e.g. SEMA3B and BTG2." (PMID 30863497, 2019). "In the current study, we have generated iFGFR1-expressing DCIS.COM cell lines and used these cell lines as a model to study the impact of FGFR1 signaling on the growth, progression and gene expression of breast DCIS tumor cells." (PMID 30111373, 2018). "The β-values of GDNF and FGFR1 were representatively shown, and significantly lower in FAP IME neoplasms than sporadic IME CRC (P = 3 × 10−5 and P = 0.02, respectively)." (PMID 30220972, 2018). "This phenomenon of co-localising chr8:ZNF703/FGFR1 and chr11:CCND1 amplicons tends to be seen in ER-positive tumours, among patients diagnosed at an older age." (PMID 30252041, 2018). "Surprisingly, we also found that there were partial losses of certain oncogenes (FGFR1, PDGFRA, and so on) and amplifications of certain tumor suppressors (NBN, EXT1, and so on) in these cell lines." (PMID 29880898, 2018). "TNFAIP3 expression is required for FGFR1 signaling-promoted DCIS.COM cell proliferation, mammosphere growth, tumor growth and progression." (PMID 30111373, 2018). "FGFR1 amplification in head and neck SCCa is only found in HPV-negative tumors, suggesting a separate pathway of tumor progression." (PMID 29351293, 2018).
tumor (continued). "Activation of FGFR1 signaling in DCIS.COM cells induces ERK1/2 activity, EMT, and cell proliferation in culture and promotes cell-derived xenograft tumor growth and progression to invasive cancer in mice." (PMID 30111373, 2018). "The large majority of super enhancers were tumor-specific and enriched for tumor-related genes, such as PAX6, FGFRL1, FGFR1, SKI, and BOC." (PMID 30279357, 2018). "We also detected FGFR1 and AXL activation in tumor cells resulting from the communication with CAFs." (PMID 29946230, 2018). "In a comprehensive survey of gene fusions across different solid tumor histologies, the authors described a wide-ranging distribution of FGFR1, FGFR2, and FGFR3 fusions across 8 of 20 tumor types analyzed." (PMID 28030802, 2017). "Most known oncogenes (e.g. EGFR, FGFR1, MYC, ERBB2) or tumor suppressors (e.g. CDKN2A, NOTCH1) were detected to reside within the focal SCNA regions." (PMID 29348864, 2017). "Sulfatinib, a potent oral kinase inhibitor targeting VEGFR, FGFR1, and CSF1R with good selectivity, has demonstrated anti-angiogenic and anti-tumor activity in preclinical studies (Hutchison MediPharma, unpublished data)." (PMID 28159938, 2017). "We also observed that the Shannon diversity indices for c-MYC and FGFR1 copy number variation were correlated, again suggesting that the degree of ITH in a tumor is an intrinsic feature of that tumor." (PMID 29228597, 2017). "Regorafenib is a small-molecule inhibitor of multiple protein kinases and inhibited tumor angiogenesis through targeting VEGFR1, 2 and 3, PDGFR-β, FGFR1, Kit, RAS/RAF/MEK/ERK pathway and so on." (PMID 28489887, 2017). "Previous work demonstrated that FGFR1 genomic amplification and increased FGF2 mRNA levels correlated with response to GSK3052230 in tumor xenograft models." (PMID 27223434, 2016). "AZD4547 is a highly selective and potent ATP-competitive TKI of FGFR1–3 and inhibited recombinant FGFR kinase activity in vitro and suppressed FGFR signaling and growth in tumor cell lines with deregulated FGFR expression." (PMID 26000013, 2015). "Basic fibroblast growth factor (bFGF or FGF-2) and its receptor (FGFR-1, CD331) have been targeted in pre-clinical mouse models to evaluate their anti-angiogenic and anti-tumor effects." (PMID 26510973, 2015). "In summary, these results show that blocking both the FGFR1 and EGFR signaling pathways significantly delays tumor recurrence." (PMID 26581390, 2015). "Examination of PDAC sections revealed that a significant percentage of myofibroblasts at the invading tumour front had nuclear FGFR1 and FGF2, compared to myofibroblasts in the central core of the tumour." (PMID 24503018, 2014). "We observed a broad distribution of the fibroblast growth factor receptors FGFR1, FGFR2 and FGFR3 fusions—in particular FGFR3–TACC3 fusions—across eight of the 20 tumour types analysed." (PMID 25204415, 2014). "This downregulation promoted tumor growth and progression through reduced post-transcriptional repression of FGF-2 and its receptor FGFR1, which act on both stromal and tumor cells to enhance cancer cell survival, proliferation, and migration." (PMID 24598126, 2014). "This further emphasises the possible role of nuclear FGFR1 and FGF2 in driving PDAC tumour invasion." (PMID 24503018, 2014). "In contrast, FGFR1, the partner of KLB activated by FGF21, is widely expressed in adipocytes, normal luminal epithelium and tumor cells (orange staining)." (PMID 24279986, 2013). "Transcriptional and protein analyses showed that FGFR1 (P = 0.006 and P<0.01, respectively) and IGFBP5 (P = 0.0002 and P = 0.006, respectively) were up-regulated in the tumours when compared with the adjacent normal myometrium." (PMID 23483937, 2013). "miR-9 has been shown to target fibroblast growth factor receptor 1 (FGFR1) and CDK6 in ALL and caudal-type homeobox 2 (CDX2) in GC, suggesting a tumor-suppressive function." (PMID 24348513, 2013).